SNORA70C (small nucleolar RNA, H/ACA box 70C)
Synonyms: U70C
Gene: Small nucleolar RNA gene on chromosome 9 (117,181,066 to 117,181,200, reverse strand). Ensembl gene ENSG00000207268.
Gene Ontology:
Biological process: RNA processing
Cellular component: nucleolus
Homologues: Orthologues: chimpanzee SNORA70 (100% identical). Paralogues in human: SNORA70G (93% identical), SNORA70H (93% identical), SNORA70J (91% identical), SNORA70 (90% identical), SNORA70I (90% identical), SNORA70B (90% identical), SNORA70 (87% identical), SNORA70D (87% identical), SNORA70F (87% identical), SNORA70 (86% identical), SNORA70E (86% identical), SNORA70 (84% identical), and 13 more.